CXCR4 (C-X-C motif chemokine receptor 4)
Diseases named in the same sentence as CXCR4 in open-access papers (continued):
Sharing a sentence is not in itself a finding about the gene and the disease.
cancer (continued). "CXCL12/CXCR4 signaling represents an important delivery target for cancer cells." (PMID 33233846, 2020). "Recent studies confirmed a wide expression of CXCR4 in the tumors with a consequent implication of this receptor in a panel of pathological processes such as cell proliferation, migration, metastasis and cancer emergence and progression." (PMID 32232002, 2020). "Furthermore, in NSCLC, circFGFR1 (hsa_circ_0084003) expression increased in cancer tissues and promoted cell migration, invasion, and immune evasion by interacting with miR-381-3p to target CXCR4." (PMID 32943996, 2020). "The CXCL12/CXCR4/CXCR7 axis is a potential target for cancer therapies." (PMID 33363463, 2020). "Anti-CXCR4 scFvs increased the Bax/Bcl-2 ratio in all three cancer cell lines." (PMID 33392074, 2020). "Recently, the function of CXCR4 in the cancer immune cycle has been extensively addressed." (PMID 32972006, 2020). "In particular, the upregulation of CXCL12 (formerly known as Stromal derived factor 1, SDF-1) and of its cognate receptor CXCR4 significantly correlates with metastasis and poor cancer prognosis, as reported in a comprehensive review article by Wang and colleagues." (PMID 33233846, 2020). "CXCR4 overexpression is correlated with poor prognosis in cancer therapy." (PMID 33392074, 2020). "The receptor CXCR4 is the most studied of all chemokine receptors in cancers." (PMID 32340161, 2020). "Furthermore, many studies have determined that CXCL12/CXCR4 axis potentiates proliferation, angiogenesis, invasion and migration of various cancers, including glioma, colorectal carcinoma, renal cancer, pancreatic cancer and ovarian cancer." (PMID 33129326, 2020). "As the cytoskeleton F-actin was considered to be bounded up with various cancer biology mainly includes cell migration and invasion as well as in self-renewal, CXCR4 might exert a crucial role in stem maintenance and migration of GICs." (PMID 31382985, 2019). "Moreover, stromal cell-derived factor 1 (SDF-1), which is the ligand for CXCR4, is also expressed in various types of cancers." (PMID 31744214, 2019). "Interestingly, CXCR4 has been shown to be selectively present on cancer initiating cells (CICs) derived from several solid tumors and they play a critical role in regulating carcinogenesis." (PMID 31382985, 2019). "Our studies demonstrate, for the first time, that anti-CXCR4 ADCs may offer enhanced therapeutic benefit over existing anti-CXCR4 antibody therapies to aggressive haematological cancers and provide benefit to solid tumours containing CXCR4+ cancer cells." (PMID 30792442, 2019). "To test whether CXCR4:ADC/antibody internalization rates differ between normal and cancer cells, we measured the kinetics of anti-CXCR4 h17-NV.TS (antibody backbone of ADC 713) delivery to lysosome in human cancer cells and normal PBMCs in vitro." (PMID 30792442, 2019). "We found that cancer cells sort anti-CXCR4 antibody to lysosome at higher rate than normal PBMCs." (PMID 30792442, 2019). "As expected, we also found miR-204 expression negatively correlated with CXCR4 (r = −0.5636, P=0.0002) in cancer tissues, indicating that miR-204 could suppress CXCR4 expression in vivo." (PMID 30940776, 2019). "However, CXCR4 is also expressed in haematopoietic cells and other normal tissues, raising safety challenges to the development of anti-CXCR4 ADCs for cancer treatment." (PMID 30792442, 2019). "We address the molecular signature of CXCR4 and how this molecule and cells expressing it are involved in either normal (maintaining stemness or inducing differentiation) or abnormal (developing cancer and other pathologies) events." (PMID 30791675, 2019).
cancer (continued). "For instance, though PBMCs showed a slower CXCR4:antibody internalization rate relatively to cancer cells, one could expect that increases in DAR can significantly augment payload delivery and thereby, toxicity to normal CXCR4+ tissue." (PMID 30792442, 2019). "Increases in the number of CXCR4+ cells may be involved in inflammation/stem cell migration normally, and cancer/malignancy abnormally." (PMID 30791675, 2019). "Aberrant CXCR4 expression has been observed in more than 23 human cancers." (PMID 31428099, 2019). "Several CXCR4 inhibitors have been developed to treat these diseases, especially cancer." (PMID 30791675, 2019). "CXC chemokine receptor 4 (CXCR4) has been suggested to play a critical role in cancer metastasis." (PMID 30177838, 2019). "This heteromerization might enable cannabinoids to indirectly reduce the invasive properties of cancer cells by inhibiting the effects of CXCR4 agonists." (PMID 31024307, 2019). "For example, CXCR4-directed PET/CT might help to visualize receptor positive cancer stem cells (and their niche) which are considered to be especially resistant to radiation or chemotherapy." (PMID 31475113, 2019). "Furthermore, microarray analysis showed modulation of proapoptotic and cancer-related genes induced by CXCR4-tropic strains starting from 24 h after infection, whereas CCR5 viruses modulated the expression of genes not correlated with apoptotic-pathways." (PMID 31234437, 2019). "PDAC tumors have a subset of highly overexpressed (and highly expressed in terms of magnitude) chemokine receptors (CCR6, CCR7, CXCR3 and CXCR4) not expressed in PDAC cancer cells but likely associated with immune cells and their activation." (PMID 31765370, 2019). "In this regard, blockade of CXCR4 might be a valuable approach to prevent the detrimental interaction of cancer and bone remodeling cells and the development of osteolytic lesions." (PMID 31572390, 2019). "CXCR4 is expressed by almost all cancer types, suggesting that the CXCR4/SDF-1α pair may be involved in site-specific metastasis formation in a large number of malignant diseases." (PMID 31219799, 2019). "Second, CXCR4-overexpressing cancer cells can then migrate along CXCL12 gradients." (PMID 31810195, 2019). "The interaction between SDF-1 and CXCR4 also plays an important role in cancer metastasis." (PMID 31615145, 2019). "However, this ligand also binds ACKR3, an atypical chemokine receptor that modulates CXCR4 functions and is overexpressed in multiple cancer types." (PMID 31507535, 2019). "Our manuscript is the first proof-of-concept study to utilize gain-of-function CXCR4 to enhance bone marrow homing of primary human NK cells and will set the stage for a new line of research focusing on directing adoptively infused immune cells to the cancer." (PMID 31231387, 2019). "We found predominant and dense interaction networks of genes engaged in neural differentiation, including the well-characterized neuroendocrine regulator somatostatin (SST) and its receptor, as well as CXCR4 and CXCR7, two chemokine receptors well-implicated in cancer metastasis." (PMID 31882655, 2019). "Most of these small CXCR4 antagonistic molecules have been targeted to cancers." (PMID 30791675, 2019). "CXCR4 is overexpressed in many human cancers, with numerous studies demonstrating differential expression patterns (nuclear, cytoplasmic, and membrane) which translated in differences in biological behavior of cancers." (PMID 29666622, 2018). "Remarkably, defects in endocytic trafficking of CXCR4 may contribute to increased surface expression and cancer progression." (PMID 29666622, 2018). "Therefore, molecule inhibitors targeting the SDF-1 CXCR4 signaling are considered in cancer therapy." (PMID 30349420, 2018). "It is not clear, whether these effects on DCs might decrease the efficacy of anti-cancer immune responses upon CXCR4 inhibition." (PMID 30622535, 2018).
cancer (continued). "However, the novel involvement of CXCR7 as a high affinity‐binding partner of CXCL12 begs for reconsideration of the whole CXCR4 paradigm in the context of cancer biology." (PMID 29460395, 2018). "Therefore, MDA-MB-231 cells treated with or without actein were subjected to real-time PCR to assess the regulation of CXCR4 gene expression on cancer cells." (PMID 30618758, 2018). "Furthermore, this axis has also been recognized as a prognostic marker in several tumors and preclinical models; signifying that metastasis is mediated by CXCR4 activation and migration of cancer cells towards CXCL12 expressing organs." (PMID 30383826, 2018). "Moreover, CD133+ and CXCR4+ are reported to involve in cancer stem cell phenotype in various cancer types." (PMID 29747452, 2018). "SDF1/CXCR4 and AnnexinA7 play important roles in many physiological and pathological conditions, but the molecular association between them in cancer cells has not been studied thus far." (PMID 29783989, 2018). "The C-X-C chemokine receptor type 4 (CXCR4, CD184) pathway is a key regulator of cancer metastasis." (PMID 29973594, 2018). "CXCR4 is also broadly expressed and is frequently overexpressed in cancer." (PMID 29666622, 2018). "(Patho)physiological role of SDF1/CXCR4 signaling and targeting in cancer." (PMID 30622535, 2018). "The C-X-C chemokine receptor type 4 (CXCR4) pathway is a key regulator of cancer metastasis." (PMID 29973594, 2018). "SDF-1 release of cancer cells as well as CXCR4 signaling in MDSCs could be abrogated by COX2 inhibition." (PMID 30622535, 2018). "Interestingly, CXCL12 is also expressed by cancer cells in TME and, in coordination with CXCR4, regulates the migration of the cancer cells for metastasis." (PMID 30220913, 2018). "CXCR4 plays a key role in cancer pathogenesis, progression, and metastasis." (PMID 30191351, 2018). "CCL7 and CXCR4 are well known chemokines that promote cancer progression." (PMID 29890660, 2018). "Its use could also increase therapeutic precision by selecting candidate patients with high CXCR4 overexpression, who are likely to be sensitive to the nanoconjugate, and determining CXCR4+ cancer cell fraction along time to monitor their response." (PMID 30190334, 2018). "This hypothesis was first tested for CXCR4, and in 2009, CXCR4 became the second GPCR shown to utilize a C3BM signaling mechanism in cancer cells." (PMID 30158935, 2018). "Furthermore, AREG affected downstream molecules like BIRC5, CCNA2, CCNB2, TOP2A, MMP9, MMP1, CXCR4, have roles in development and progression of various types of cancers." (PMID 30517191, 2018). "Besides, CXCR4 is also overexpressed in more than 20 types of cancers, including melanoma, glioma, acute myelogenous leukemia, chronic lymphocytic leukemia, breast, prostate, renal, pancreatic, ovarian, cervical, colon, and small-cell lung cancers." (PMID 29686536, 2018). "While CED is not a poor choice for drug delivery in GBM, our data imply that therapeutic use of CED may benefit from supplementation with CXCR4 blockade to prevent undesirable consequences on cancer cell invasion." (PMID 30451884, 2018). "It is also involved in the expansion of CXCR4-positive cancer stem-like cells in RCC38." (PMID 30082842, 2018). "The CXCR-4 is another receptor involved in the growth and metastasis of cancer cells." (PMID 28660349, 2018). "CXCR4 has been described as an MDSC activation marker in cancer." (PMID 29868036, 2018). "We used CED in an orthotopic, murine model of GBM to test the hypothesis that convective flow directly stimulates cancer cell invasion in vivo and examine the dependence of this response on CXCR4 signaling." (PMID 30451884, 2018). "Interestingly, the urotensin II receptor (UR2R) which appeared in chordates has properties reminiscent of CXCR4, including chemotaxic properties and involvement in cancer metastasis, along with location in the central nervous system." (PMID 29912865, 2018).
cancer (continued). "Our results support a vast body of literature that validates CXCR4 as a promising target for cancer therapy and demonstrate that small-molecule CXCR4 antagonists have novel therapeutic potential for HIV infection beyond their activity against viral entry by blocking Nef induced T-cell depletion." (PMID 29682200, 2018). "In addition to metastasis, CXCR4 signaling has been shown to mediate many pro-tumorigenic functions in cancer cells, including proliferation, survival, angiogenesis, and chemoresistance." (PMID 29930538, 2018). "CXCR4, a G-protein coupled receptor, is reported to mobilize cancer cells in response to CXCL122." (PMID 29973594, 2018). "Thus, the current findings at least partially demonstrated that spinal NMDAR was critically involved in CXCR4 signaling-mediated cancer pain." (PMID 28638088, 2017). "This suggested a potential advantage to the noninvasive assessment of CXCR4 expression in cancer." (PMID 29088715, 2017). "Furthermore, we present evidence that UHRF1 deficiency leads to the induction of EMT by activating the CXCR4/AKT-JNK/IL-6 signaling pathway, thereby contributing to the expansion of cancer stem-like cells." (PMID 28584306, 2017). "These distinct pharmacodynamic effects in two different classes of CXCR4 inhibitors are clinically important and should be carefully considered when designing combination studies with immune checkpoint inhibitors or other agents for cancer therapy." (PMID 29212254, 2017). "Additionally, its silencing in cancer-derived cell lines led to down-regulation of chemokine (C-X-C motif) receptor 4 (CXCR4) and reduced cell proliferation." (PMID 27664137, 2017). "CXCR4 and its downstream pathways have been widely investigated in cancer and EMT." (PMID 28774348, 2017). "Moreover, IFN-DCs exposed to conditioned medium (CM) from RI-treated SW620, selectively increased CXCR4 expression on the membrane compared to that of cells exposed to CM from NT cancer cells." (PMID 28439087, 2017). "Interestingly, CQ and HCQ can induce CXCR4 internalisation in cancer stem cells, making these cells less sensitive to CXCL12 signals." (PMID 29225688, 2017). "Thus, targeting of the SDF-1/CXCR4 axis has been suggested as a treatment strategy in cancer suppression." (PMID 28890883, 2017). "The activation of CXCL12/CXCR4 axis enhances migration and invasion of cancer cells, thus leading to metastasis and may regulate antitumor immune response through T cells access." (PMID 28774348, 2017). "Furthermore, increased expression of CXCR4 in human cancer cells indicates that CXCR4 is critical for resistance to chemotherapy." (PMID 29117108, 2017). "One advantage of CXCR4-KLA is that it can be easily modified to target other cancer cells." (PMID 28196146, 2017). "Furthermore, past studies have indicated that miR-338 can affect cancer invasion and metastasis by reducing CXCR4 expression, so as to slow the development of BCP." (PMID 28108674, 2017). "CXCR4 is ubiquitously expressed in many human cancer cell lines." (PMID 28403883, 2017). "However, all these approaches only exhibit modest anticancer effects, presumably because the drugs only block the activities of SDF-1/CXCR4 axis instead of eliminating the cancer cells." (PMID 28196146, 2017). "In addition, activation of the Akt pathway is reportedly involved in CXCR4-mediated cell signaling in cancer cells, and this signaling pathway is utilized by CRC cells for invasion, metastasis, and proliferation." (PMID 29117108, 2017). "The angiogenic actions mediated by the CXCL12/CXCR4 transduction pathway in cancer may involve the activation of EPCs, as well as the recruitment of additional pro-angiogenic molecules such as VEGF." (PMID 29240722, 2017). "Furthermore, the spinal CaMKII/CREB pathway is a critical downstream target for CXCR4-mediated neuronal sensitization and cancer pain hypersensitivity." (PMID 28638088, 2017).
cancer (continued). "Together, these data have suggested that CXCR4 expression on cancers can serve as a correlate of aggressive biological behavior and that CXCR4 itself could be a potential therapeutic target." (PMID 29088715, 2017). "Moreover, for other cancers where high frequencies of CXCR4 staining have been reported, such as primary tumors of the breast, colon, and prostate, we detected CXCR4 in fewer than 10% of cases." (PMID 29088715, 2017). "CXCR4 has been considered as a target for (adjuvant) cancer therapy." (PMID 27896627, 2017). "Consequently, there has been interest in developing new imaging tools for detecting and quantifying CXCR4 on cancers in order to aid in prognostication and treatment." (PMID 29088715, 2017). "It is likely that some of the miRNAs might involve in the activation of CXCL12/CXCR4 axis and therefore play an important role in cancer progression and metastasis." (PMID 28176874, 2017). "Spinal blockade of the CXCR4-CaMKII/CREB pathway may be a potential analgesic therapy for cancer pain management." (PMID 28638088, 2017). "Exposure of MSCs to hypoxia also leads to enhanced migration of cells through modulation of CXCR4; however, these cells may adopt a cancer-like phenotype following hypoxic preconditioning due to accumulation of reactive oxygen species." (PMID 28705238, 2017). "Furthermore, CXCL12 knockdown by application of two different shCXCL12 or the CXCR4 antagonist AMD3100 decreased the survival of cancer cells." (PMID 28489070, 2017). "MiR-125b was a critical mediator of CXCL12/CXCR4 axis in cancer EMT." (PMID 28176874, 2017). "We further analysed CXCL12/CXCR4 signalling in cancer progression." (PMID 28489070, 2017). "Furthermore, CD133+CXCR4+ cancer cells have a highly aggressive metastatic capacity compared to CD133+CXCR4− cells." (PMID 29100290, 2017). "We hypothesized that miRNAs might be critical downstream mediators of CXCL12/CXCR4 axis involved in cancer invasion and chemoresistance in CRC." (PMID 28176874, 2017). "Acquirement of migratory functionality might play an important role in the development of metastasis: high expression of CXCR4 on cancer cells might induce their migration to tissue with high levels of CXCL12." (PMID 28356064, 2017). "Chemokine receptor 4 (CXCR4) is overexpressed in many cancers and a potential drug target." (PMID 27896627, 2017). "Among all CSC surface markers, CXCR4, which is a unique receptor for stromal cell -derived factor-1 (SDF-1), has been shown to be particularly important, since the CXCR4/SDF-1 axis mediates the chemo-attractive effects that allow cancer cells to detach, migrate and seed to distal tissue." (PMID 27835894, 2016). "Inhibition or over-expression of CXCR4 modifies cancer cell propensity to colonise bone marrow." (PMID 27782035, 2016). "In fact, CXCR4 is the most common chemokine receptor overexpressed in human cancer." (PMID 27876058, 2016). "CXCR4 is highly expressed in 23 different cancers of various origins including GBM." (PMID 27382437, 2016). "The SDF-1/CXCR4 axis is a potential chemoattractant system that regulates cell migration and homing, and plays an important and unique role in the regulation of stem/progenitor/cancer cell trafficking." (PMID 27835894, 2016). "Notably, CXCL12/CXCR4 appears to be important for site-specific metastasis of several cancers; CXCR4-positive cancer cells invade along CXCL12 gradients thus promoting metastasis to CXCL12-expressing organs such as lymph nodes, lung, livers and bone." (PMID 27213454, 2016). "Similarly, inhibition of CXCR4 by pharmacological agents or neutralising antibodies decreases metastatic cancer cell dissemination to the lung and bone." (PMID 27782035, 2016). "Furthermore, in various cancer models metastasis of cancer cells was revealed to be mediated by CXCR4 activation and directed migration towards CXCL12 expressing organs." (PMID 26920352, 2016). "The Lgr5+/CXCR4+ cancer cells were generated by co-transduction with both AAVs." (PMID 27835894, 2016).